PTK6 (protein tyrosine kinase 6)
Diseases named in the same sentence as PTK6 in open-access papers (continued):
Sharing a sentence is not in itself a finding about the gene and the disease.
cancer (continued). "The deregulated expression of PTK6 was observed in various human cancers." (PMID 23497344, 2013). "However, how PTK6 expression in this malignant tumor is modulated and functions still needs more investigations." (PMID 23497344, 2013). "PTK6 may promote human cancer growth by modulating signaling via growth factors receptors, such as IGF-1R and ErbB2." (PMID 20668531, 2010). "In order to deepen our understanding of the relationship between PTK6 and immunity, a comprehensive analysis of 22 immune cell populations was conducted, with the aim of elucidating the intricate interplay between PTK6 and immune cells across various types of cancer." (PMID 38573548, 2024). "Therefore, further detailed investigation of ALT-PTK6 and PTK6 interactions in cancers may be a fruitful avenue of research to develop a highly-specific PTK6 inhibitor." (PMID 37509364, 2023). "Moreover, lowering PRKCA (protein kinase C alpha) and PTK6 (protein tyrosine kinase 6) could also inhibit cell growth, proliferation, and cancer progression." (PMID 37834191, 2023). "In addition, several studies have reported the role that PTK6 played in a variety of cancers." (PMID 36405012, 2022). "According to the studies presented above, PTK6 might be an oncogene in some cancers." (PMID 36405012, 2022). "Together, our results uncovered PSPC1-CT131 as a first in its class dual inhibitor targeting oncogenic PSPC1 and PTK6/β-catenin oncogenic subcellular translocation switch and might be a promising avenue for exploring clinical interventions to prolong the survival of cancer patients." (PMID 31844057, 2019). "Previous studies indicated that nuclear tyrosine kinase PTK6 might function as a tumor suppressor to phosphorylate RNA-binding proteins, such as Sam68, to restrain their proliferative and anti-apoptotic functions in divergent cancer cells and tissues." (PMID 31844057, 2019). "Thus, further studies are needed for a better understanding of the role of PTK6 in cancer biology." (PMID 27311570, 2016). "In different cancers, the intracellular location of PTK6 may be different." (PMID 27311570, 2016). "Moreover, both 3p21.3 (MST1R) and 20q13 (PTK6) contain putative oncogenes, which are frequently located in regions of genomic amplification in cancer." (PMID 16508639, 2006). "Protein tyrosine kinase 6 (PTK6) was identified as a direct target of trifolirhizin, which is known to be an important target of various cancers." (PMID 39860257, 2025). "While SRC mRNA expression is more widely distributed, distinct subsets of cells coexpress both PTK6 and SRC in both cancers." (PMID 36228719, 2022). "Moreover, PSPC1, as a substrate of nuclear PTK6, is the contextual determinant of PTK6 nucleocytoplasmic shuttling and modulates the switch of tumor-suppressive PTK6 in the nucleus of normal or premalignant cells to oncogenic PTK6 in the cytoplasm of malignant cancer cells." (PMID 34340703, 2021). "Recognized cancer-related kinases are again observed in this set, including ERBB2, FGFR2, PTK6, RAF1 and RON (MST1R) as well as 22 understudied kinases." (PMID 29643987, 2018). "The signaling kinases like AKR/J thyoma protein kinase (Akt), which is responsible for phosphorylation of tau and protein tyrosine kinase 6 (PTK6), that is highly expressed in various cancers are degraded by CHIP." (PMID 27757073, 2016). "Protein tyrosine kinase 6 (PTK6, also called BRK) is a SRC-related intracellular tyrosine kinase expressed in normal epithelia and cancer." (PMID 25153721, 2014). "Future studies on the cellular function and interaction pathways of PTK6 and its potential role in the development of LSCC cancer will be helpful for further understanding of the progress of this malignant tumor and improving clinical therapies." (PMID 23497344, 2013). "The 20q13.33 region overlapped with several cancer related genes such as CDH4, LAMA5, RPS21, KIAA1510, TNFRSF6B (M68, DcR3), RTEL, EEF1A2 and PTK6." (PMID 24165089, 2013).
cancer (continued). "PTK6 also influences EMT, a crucial process in cancer metastasis." (PMID 40510341, 2025). "Cancer tissues from three different patients exhibit higher expression of PTK6 and stronger activation of both PTK6 and SRC in comparison to the nonmalignant tissue." (PMID 36228719, 2022). "In this study, we investigated the differential expression of PTK6 in tumor tissue compared to nontumor tissue as well as in various stages of cancer." (PMID 36405012, 2022). "We show that ectopic active PTK6 enhances activating phosphorylation of SRC at Tyr416, and knockdown of endogenous PTK6 results in downregulation of SRC Tyr416 phosphorylation in different cancer cell lines." (PMID 36228719, 2022). "Indeed, in premalignant cancer cells with low PSPC1 expression, PTK6 is sequestered by its tyrosine-phosphorylated substrate and interacts with PSPC1-phospho-Y523 in the nucleus to suppress the tumorigenic functions of PSPC1." (PMID 34340703, 2021). "Protein Tyrosine Kinase 6 (PTK6) encodes a cytoplasmic nonreceptor protein kinase, implicated in processes of proliferation, apoptosis, migration, and invasion in cancer cells." (PMID 34721517, 2021). "PSPC1 upregulation or PSPC1-Y523F mutation loses nuclear sequestration of tumor suppressive PTK6 to promote cancer EMT, stemness and metastasis via oncogenic cytoplasmic translocation of PTK6 and nuclear translocation of β-catenin, which interacts with PSPC1 to promote Wnt3a autocrine signaling." (PMID 31844057, 2019). "In addition to PTK6, we also observed modest inactivity of FYN, another Src kinase, which plays an important role in cancer as well as diseases of the central nervous system." (PMID 31278310, 2019). "The mRNA and protein levels of PTK6 in cancer tissues were higher than those in adjacent non-tumorous cervical tissues." (PMID 27311570, 2016). "qRT-PCR results showed that the mRNA level of PTK6 in cancer tissues was higher than that in adjacent non-tumorous cervical tissues, and the range of fold increase was 3.6–11.9." (PMID 27311570, 2016). "Although some nuclear staining of PTK6 was found in low-grade carcinomas (arrows), it was absent from most high-grade carcinomas." (PMID 25153721, 2014). "Since PTK6 and SRC target many of the same substrates and PTK6 can promote SRC activation, drugs that target both kinases may have greater efficacy than targeting either kinase alone in cancer therapy." (PMID 36228719, 2022). "Similarly, Western blotting showed that the cancer tissues had higher levels of PTK6 protein expression compared with matched non-tumorous tissues." (PMID 27311570, 2016). "Protein Tyrosine Kinase 6 (PTK6) is a non-receptor type tyrosine kinase that may be involved in some cancers." (PMID 24788754, 2014). "However, a clear role for PTK6 in cancer has not been well-studied." (PMID 25748447, 2015). "PTK6 is expressed in the normal human mammary gland, but does not appear to be active and may have kinase-independent functions that are distinct from its cancer promoting activities at the membrane." (PMID 25153721, 2014). "Moreover, PTK6 high mRNA expression has been reported in the cancers of the bladder, pancreas, and gastric cancer, but its protein expression and functions have not been validated in these cancers." (PMID 23758975, 2013). "Multiple studies indicate that targeting PTK6 and SRC may provide an advantage in cancer therapy although specificity of these inhibitors is lacking." (PMID 36228719, 2022). "PTK6 (or Brk) belongs to the nonreceptor tyrosine kinase FRK/PTK6 family and is composed of Src homology 3 (SH3), Src homology 2 (SH2) and kinase (SH1) domains; it is known to be upregulated in multiple cancer types and normal epithelial cells." (PMID 34340703, 2021).
tumor (63 papers, 2007 to 2026). "Initially, bioinformatics analysis was employed to investigate the association between PTK6 expression and tumor." (PMID 38573548, 2024). "RNA-seq analyses further confirmed the correlation between risk of invasive progression and high expression of ERBB2 (HER2), PTK6 and Ki67, which have all been described previously as potential risk factors for tumor progression." (PMID 37116492, 2023). "As previously reported, high expression of ptk6 (Brk) was significantly associated with an increasing tumour (TNM) stage (p = 0.02) and resulted in reduced overall and disease-free survival." (PMID 35327957, 2022). "Of particular note is the finding that high PTK6/ALT-PTK6 ratios were associated with ER-ve tumours, i.e., those where treatment options are more limited." (PMID 35327957, 2022). "Signaling by PTK6 is implicated in controlling the differentiation of normal epithelium and tumor growth." (PMID 32328353, 2020). "PSPC1 is known to act as an pro-metastatic driver in HCC4, whereas nuclear PTK6 is implicated in tumor suppression." (PMID 31844057, 2019). "In multivariate analysis, the disease-free survival of patients of ⩾240 months was directly associated with the protein expression level of PTK6 (P⩽0.001), but was also inversely associated with nodal status (P⩽0.001) and tumour size (P⩽0.01)." (PMID 18781181, 2008). "Here, the stepwise selected parameters were lymph node status (risk factor 2.1), PTK6 expression (0.6), and tumour size (1.5)." (PMID 18781181, 2008). "Performing multivariate analysis for an interval of 60 months, the tumour size (risk factor 1.9), PTK6 expression (0.6), HER2/neu (1.0), and lymph node status (1.7) were independently prognostic." (PMID 18781181, 2008). "The stepwise selected parameters for a disease-free survival of patients of >240 months were lymph node status (risk factor 2.1), PTK6 expression (0.6), and tumour size (1.6)." (PMID 18781181, 2008). "Performing multivariate analyses only with the newly added cases, the stepwise selected parameters for a disease-free survival of patients of >240 months were lymph node status (risk factor 2.3), tumour size (1.6), and PTK6 expression (0.7)." (PMID 18781181, 2008). "In multivariate analysis for metastases-free survival of >240 months, the stepwise selected parameters were tumour size (relative risk 3.1), PTK6 expression (0.4), and number of positive lymph nodes (1.2)." (PMID 17299391, 2007). "The stepwise selected parameters for a distant recurrence-free survival of patients were tumour size (relative risk 3.1), number of positive lymph nodes (1.2), and PTK6 expression (0.4)." (PMID 17299391, 2007). "This suggests that high PTK6 expression may decrease the tumor’s immune evasion by suppressing immune checkpoint molecules, thereby enhancing the tumor microenvironment’s susceptibility to immune clearance during treatment." (PMID 40809015, 2025). "Consequently, further experimentation utilizing in vivo experiments are required to investigate the underlying biological mechanisms of PTK6, as well as the interactions between tumor immunity and PTK6 in LUAD." (PMID 38573548, 2024). "Interestingly, also in mouse models, loss of PTK6 conferred resistance to tumor development following treatment with the colon carcinogen azomethane (AOM)." (PMID 37509364, 2023). "On the other hand, nuclear PTK6 phosphorylation causes a tumor suppressive role." (PMID 37509364, 2023). "A list of lincRNAs is associated with PTK6 (green module), involved in tumor growth." (PMID 30485296, 2018). "The observed anti-tumor effects by PTK6 kinase inhibitors may be caused by off-target kinase inhibition." (PMID 29879184, 2018). "The level of PTK6 expression was significantly associated with tumor grade (P = 0.020)." (PMID 27311570, 2016).
tumor (continued). "While no PTK6 P-Y342 was detected in the normal mammary gland samples, we detected membrane associated active P-Y342 PTK6 in all tumor subtypes, with the highest percentages of strong positives in the triple negative (25%) and HER2 overexpressing (25%) subtypes." (PMID 25153721, 2014). "The correlation of PTK6 protein expression with the histological tumour grade observed in our study may also support an association between PTK6 and cell differentiation." (PMID 17299391, 2007). "Furthermore, expression of PTK6 in tumours is linked with the expression of HER2." (PMID 20700126, 2010). "In addition, here, we could show that also PTEN, which belongs to the same PI3K/Akt signalling pathway, coprecipitates with PTK6 in T47D cell line, and is statistically associated with the expression of PTK6 in tumour tissue." (PMID 18781181, 2008). "Nevertheless, the expression level of PTK6 and the integrity of its key functional domains are closely related to tumor progression." (PMID 40809015, 2025). "Existing studies have shown that the enzymatic active sites of PTK6 (such as the K219 site) are crucial for its mediated signal transduction and the biological functions of tumor cells." (PMID 40809015, 2025). "PTK6 has been demonstrated to enhance various aspects of tumor progression, such as cell proliferation, migration, invasion, and survival, through the modulation of several signaling pathways, including Ras/MAPK, PI3K/Akt/mTOR, and JAK-Stat." (PMID 40809015, 2025). "The results confirmed that PTK6 expression was significantly higher in tumor tissues compared to adjacent non-tumor tissues, consistent with our previous findings that PTK6 mRNA levels are elevated in tumor tissues." (PMID 40809015, 2025). "Validation through quantitative PCR (qPCR) demonstrated a significant upregulation of PTK6 in CM tumor tissues relative to controls, with elevated expression observed in the high-risk cohort." (PMID 40809015, 2025). "In order to further investigate the potential oncogenic mechanism of PTK6 in LUAD, examinations were conducted to explore the relationship between PTK6 and the tumor immune microenvironment." (PMID 38573548, 2024). "Specifically, elevated expression of PTK6 in LUAD is associated with reduced levels of immune infiltration and checkpoint expression, thereby potentially influencing the tumor microenvironment." (PMID 38573548, 2024). "The findings indicate a significant overexpression of PTK6 in various tumor types, which correlates with clinicopathological characteristics and unfavorable prognosis." (PMID 38573548, 2024). "Ongoing studies will further clarify the mechanisms by which MARCH2 is regulated by PTK6 in the context of various oncogenic activities in multiple tumor types." (PMID 38457262, 2024). "All of those results confirm that PTK6 overexpression is an indicator in tumor immune microenvironment suppression." (PMID 38573548, 2024). "Subsequent survival analysis reveals PTK6 to be a risk factor for OS, PFI, and DSS in multiple tumor types." (PMID 38573548, 2024). "PTK6 is also highly expressed in UM samples and correlates with the prognosis of tumour patients, and experiments in nude mice have demonstrated that PTK6 promotes the growth of UM." (PMID 38467935, 2024). "Recent research indicates that the functions of PTK6 are context-dependent and vary by cell type, tumor status, and intracellular location." (PMID 37509364, 2023). "Although PTK6 plays an important role in tumor development, it can act as a promoter or inhibitor depending on the tumor type." (PMID 37932734, 2023). "One potential rationale for this role is that PTK6 nuclear targets retain the kinase in the nucleus, preventing it from enhancing growth, and exerting a tumor-suppressive action." (PMID 37509364, 2023).
tumor (continued). "Hypoxia inducible factor (HIF) 1α/2α, glucocorticoid receptor (GR), and the phosphorylated S134-GR/PELP1/HIF signaling complex have been shown to induce the expression of PTK6, thus promoting the survival and metastasis of tumor cells." (PMID 37932734, 2023). "Since then, PTK6 has been detected in several normal and tumor tissues at varying levels, where it activates a variety of oncoproteins that promote cell growth, survival, and malignant transformation." (PMID 37509364, 2023). "The results revealed the effective inhibition of tumor growth and marked reductions in tumor volume and weight following PTK6 knockdown." (PMID 35562900, 2022). "When receptor status was taken into account, a high ratio of ptk6/ALT-PTK6 transcripts was found in ER-ve tumours." (PMID 35327957, 2022). "PTK6 mRNA in tumor tissue was detected and exhibited the same tendency as in the in vitro experiments." (PMID 35401239, 2022). "PTK6 expression was shown to be significantly elevated in the majority of tumor types, including BC, according to the findings of this investigation." (PMID 36405012, 2022). "Here, we investigated the novel RNA-binding function of FSCN1 and found that FSCN1 inhibits protein tyrosine kinase 6 (PTK6) expression by binding to its pre-mRNA, thus facilitating tumor progression in ESCC." (PMID 35401239, 2022). "Other studies have identified a link between PTK6, tumor cell survival, proliferation, cell cycle regulation, apoptosis, and metastasis." (PMID 34884984, 2021). "Although PTK6 was elucidated to be a tumor suppressor in normal epithelia, it promoted the azoxymethane-induced colon tumorigenesis in mouse models via activating STAT3." (PMID 34551797, 2021). "Consistent with the IHC results, western blot analysis also demonstrated a higher PTK6 expression in five out of eight fresh CRC tissues than the matched non-tumor tissues." (PMID 34551797, 2021). "The aberrantly elevated expression of PTK6 was detected in tumor tissues of CRC patients in both TCGA + GTEx and GEO (GDS4382-GPL570) databases." (PMID 34551797, 2021). "One key tumor-related protein that was dysregulated by miR-214 gene editing was PTK6, a gene known to regulate oncogenesis in PCa cells." (PMID 34884984, 2021). "Collectively, our results suggested that the dynamic interaction of PSPC1 or PSPC1-Y523F with PTK6 or β-catenin modulated autocrine Wnt3a/β-catenin signaling to synergize tumor progression in HCC." (PMID 31844057, 2019). "We further identify PSPC1-CT131 as an inhibitor to abrogate the oncogenic functions of PSPC1 and PTK6 and to interfere with oncogenic translocations of PTK6 and β-catenin, thus suppressing tumor progression in HCC models." (PMID 31844057, 2019). "In contrast, these tumor progression signatures were significantly downregulated in PSPC1/PTK6- and PSPC1-CT131-treated HCC cells." (PMID 31844057, 2019). "Together, our results demonstrated that the synergized PSPC1/PTK6/β-catenin axis regulates tumor migratory ability and malignant phenotype leading to tumor growth and metastasis in a mouse orthotopic HCC model." (PMID 31844057, 2019). "Our finding of PSPC1 as a substrate that sequesters PTK6 tyrosine kinase in the nucleus provides an additional example for the crucial role of tyrosine phosphorylation of PTK6 nuclear substrates in tumor suppression." (PMID 31844057, 2019). "In contrast, a decrease in the expression of p-Y523-PSPC1 is a warning of the synergistic oncogenic activation of PSPC1, nuclear β-catenin and cytoplasmic PTK6 that facilitates tumor progression in HCC patients." (PMID 31844057, 2019). "PTK6 inhibitors as well as a structural analogue without inhibiting PTK6 kinase were profiled for broad kinase selectivity, and applied to probe the specific role of PTK6 kinase activity in tumor cells." (PMID 29879184, 2018). "It was found that while PTK6 kinase activity was substantially inhibited by both Type I and II inhibitors in tumor cells, the tumor growth was only weakly suppressed." (PMID 29879184, 2018).